TAF3 (TATA-box binding protein associated factor 3)
Description:
The TFIID basal transcription factor complex plays a major role in the initiation of RNA polymerase II (Pol II)-dependent transcription. TFIID recognizes and binds promoters with or without a TATA box via its subunit TBP, a TATA-box-binding protein, and promotes assembly of the pre-initiation complex (PIC). The TFIID complex consists of TBP and TBP-associated factors (TAFs), including TAF1, TAF2, TAF3, TAF4, TAF5, TAF6, TAF7, TAF8, TAF9, TAF10, TAF11, TAF12 and TAF13. The TFIID complex structure can be divided into 3 modules TFIID-A, TFIID-B, and TFIID-C. TAF3 forms the TFIID-A module together with TAF5 and TBP. Required in complex with TBPL2 for the differentiation of myoblasts into myocytes. The TAF3-TBPL2 complex replaces TFIID at specific promoters at an early stage in the differentiation process.
Synonyms: TAF140; TAFII-140; TAFII140
Tractability: Small molecule: a structure with a bound ligand is known. PROTAC: UniProt records ubiquitination sites on it; ubiquitination databases record sites on it; its protein half-life has been measured.
Target class: Plant homeodomain; Epigenetic regulator; Reader
Gene: Protein-coding gene on chromosome 10 (7,818,497 to 8,016,631, forward strand). Ensembl gene ENSG00000165632.
Subcellular location: Nucleus
Subcellular location (Human Protein Atlas): Nuclear membrane; Nucleoplasm
Pathways (Reactome):
Gene expression (Transcription): RNA Polymerase II Pre-transcription Events; RNA Polymerase II Promoter Escape; RNA Polymerase II Transcription Initiation; RNA Polymerase II Transcription Initiation And Promoter Clearance; RNA Polymerase II Transcription Pre-Initiation And Promoter Opening
Disease: HIV Transcription Initiation; RNA Polymerase II HIV Promoter Escape; Transcription of the HIV genome
Gene Ontology:
Molecular function: histone H3K4me3 reader activity; protein binding; transcription regulator inhibitor activity; RNA polymerase II general transcription initiation factor activity; protein heterodimerization activity
Biological process: maintenance of protein location in nucleus; mRNA transcription by RNA polymerase II; negative regulation of transcription by RNA polymerase II; positive regulation of transcription initiation by RNA polymerase II; RNA polymerase II preinitiation complex assembly; positive regulation of transcription by RNA polymerase II; chromatin organization; transcription by RNA polymerase II
Cellular component: nuclear membrane; nucleoplasm; nucleus; transcription factor TFIID complex
Genetic constraint (gnomAD): Loss-of-function variants: 4 observed, 73.52 expected, observed/expected ratio (o/e) 0.0544, 90% interval 0.026 to 0.12. The upper end of that interval is the gene's LOEUF score, 0.12, which puts it in group 1 of 6, group 1 being the genes least tolerant of losing a copy. Missense variants: 920 observed, 1,111.1 expected, observed/expected ratio (o/e) 0.83, 90% interval 0.78 to 0.87. Synonymous variants: 444 observed, 432.96 expected, observed/expected ratio (o/e) 1.03, 90% interval 0.95 to 1.11.
Homologues: Orthologues: chimpanzee TAF3 (99% identical), macaque TAF3 (98% identical), rabbit TAF3 (91% identical), guinea pig TAF3 (90% identical), dog TAF3 (89% identical), pig TAF3 (88% identical), mouse Taf3 (86% identical), tropical clawed frog taf3 (68% identical), zebrafish taf3 (50% identical), Drosophila melanogaster Taf3 (30% identical). Paralogues in human: CXXC1 (10% identical).
Diseases named in the same sentence as TAF3 in open-access papers:
TAF3 is named in the same sentence as 8 diseases in open-access papers, as found by Europe PMC text mining. Sharing a sentence is not in itself a finding about the gene and the disease. The quoted sentences say what the papers report.
astroblastoma (1 paper, 2025). "This translocation is typical of astroblastomas; cases of MN1::BEND2 (also typical of astroblastomas) and MN1::TAF3 fusions have begun to be described in soft tissue sarcomas." (PMID 40141463, 2025).
atherosclerosis (1 paper, 2020). A disease characterized by the build-up of fatty material and calcium deposition in the arterial wall resulting in partial or complete occlusion of the arterial lumen. "Xpr1 and Taf3, a regulator of macrophage differentiation and a core transcription factor, which were detected in mouse PVAT, were significantly upregulated during atherosclerosis, suggesting a role in the pathogenesis of atherosclerosis." (PMID 33391033, 2020).
colon cancer (1 paper, 2014).
HIV-1 infection (1 paper, 2025). The type species of lentivirus and the etiologic agent of acquired immunodeficiency syndrome (AIDS). "Additionally, TRIM33 restrains HIV-1 infection by targeting viral integrase, while TAF3, a transcription cofactor, contributes to promotor recognition and selectivity." (PMID 39996757, 2025).
type 2 diabetes (1 paper, 2024). "In conclusion, serum magnesium concentrations are associated with genetic variability around the regions of TAF3, MUC1/TRIM46, SHROOM3, and SLC22A7 in type 2 diabetes." (PMID 38279093, 2024). "Our results suggest that genetic variation in or near TAF3, MUC1/TRIM46, SHROOM3, and SLC22A7 are associated with the regulation of serum Mg2+ concentrations which may be partially explained by renal function, in type 2 diabetes." (PMID 38279093, 2024).
tumour (1 paper, 2020). "CNGs associated with poor outcome harboured transcription factors GATA3, GATA5, MLLT10, and TAF3 frequently amplified in HBCs15,19,28,41–43, EMT markers VIM, LAMA5, and ZEB121, and several genes enriching biological processes enhancing tumour-cell migration and motility." (PMID 31969654, 2020).
TAF3 also shares sentences with these, for which no sentence is quoted: congenital heart disease (1 paper); soft tissue sarcoma (1).